VIM (vimentin)
Diseases named in the same sentence as VIM in open-access papers (continued):
Sharing a sentence is not in itself a finding about the gene and the disease.
cancer (continued). "As it’s well known that vimentin promotes cell migration and cancer exosomes increase cell mobility, we investigated whether the vimentin-binding compound would have impacts on cancer cell migration and invasion." (PMID 34305581, 2021). "However, using TMAs with a single spot per cancer, we have been able to reproduce a multitude of established associations between clinical features and molecular markers such as HER2, Vimentin and Ki67 in the past." (PMID 32143573, 2020). "Many studies on various cancer tissues have demonstrated down-regulation of epithelial markers including E-cadherin, plakoglobin and cytokeratin, as well as the up-regulation of mesenchymal markers such as N-cadherin and vimentin and expression of EMT transcription factors SNAI 1/2 and TWIST." (PMID 32817625, 2020). "Furthermore, the higher expression of vimentin and α-smooth muscle actin in the MEC cell line, compared to the HSG line, demonstrates the presence of myoepithelial cells, which are part of cancer-associated fibroblasts (CAFs) and were already visualized in MEC." (PMID 31936364, 2020). "In contrast, exogenous expression of TRPV6, led to higher levels of vimentin and slug, suggesting that TRPV6-mediated calcium influx is directly linked to the levels of EMT-markers and could in this way play a role in cancer progression." (PMID 32895467, 2020). "In addition, some vimentin molecules expressed in cancer cells migrate to the cell surface and have been identified as cancer-specific EMT markers, called cell-surface vimentin (CSV), and were shown to correlate with highly invasive and metastatic properties of cancers." (PMID 33266262, 2020). "Immunohistochemistry (IHC) and immunoreactivity scoring results showed that TCTP and vimentin were highly expressed respectively in 68/109 (62.4%) and 61/109 (56.0%) of NSCLCs and the overall expressions of both were up-regulated significantly in cancer tissues than in normal adjacent tissues." (PMID 32046740, 2020). "Increased LEF1 expression is associated with several types of cancer and has been associated in many tissues with regulation of epithelial-to-mesenchymal transition (EMT) including transcriptional activation of EMT effectors, such as N-Cadherin, Vimentin, and Snail." (PMID 32403323, 2020). "In cancer, EMT has been initially considered as a binary process with two very distinct cell populations - epithelial and mesenchymal, characterized by the loss of expression of the epithelial marker E-cadherin and the gain of the expression of the mesenchymal markers N-cadherin and vimentin." (PMID 32679765, 2020). "VIM encodes for vimentin, an intermediate filament characteristic of cells with mesenchymal phenotype, not expressed in most normal epithelia (including urothelium), nor in most carcinomas." (PMID 32102337, 2020). "Vimentin connects mechanotransduction webs within cells, from focal adhesions to cytoskeletal proteins, such as actin, microtubules, and nuclear cytoskeleton nesprins, to modulate cell spreading and adhesion, and control the directional migration of cancer cells." (PMID 31182056, 2019). "Increase in vimentin (Type III intermediate filament protein), N-cadherin (transmembrane glycoprotein) and loss of E-cadherin have been characterized as key molecular alterations during Epithelial-to-Mesenchymal Transition (EMT), a primary step in cancer metastasis." (PMID 31757995, 2019). "Moreover, the prognosis-indicative role of vimentin was shown in other cancers and diseases." (PMID 29955607, 2018). "Cancer progression is associated with a dynamic process of epithelial-to-mesenchymal transition (EMT), during which epithelial cells lose their cell polarity and cell-cell adhesion and gain migratory as well as invasive properties by downregulating E-cadherin and upregulating vimentin expression." (PMID 30069274, 2018).
cancer (continued). "In cancer stroma, normal fibroblasts have been transformed into cancer-associated fibroblasts (CAFs), which are characterised by the presence of several markers such as alpha-smooth muscle actin (α-SMA), platelet-derived growth factor-β receptor (PDGFR-β) and vimentin." (PMID 30899183, 2018). "These new findings undoubtedly will open up multiple avenues to study the broader function of vimentin and other IF proteins in cell biology and will lead to critical insights into the relevance of different vimentin levels for the invasive behaviors of metastatic cancer cells." (PMID 30505430, 2018). "Of note, liprin-α1 affects cancer cell spreading, the distribution of cell surface β1-integrins, and regulates cell edge dynamics and focal adhesion assembly in motile epithelial cancer cells via proteins including vimentin, ERC1 (ELKS/RAB6-interacting/CAST family member 1) and β1-integrin." (PMID 30005669, 2018). "Additionally, other markers could influence the progression and prognosis of cancer through regulating vimentin expression." (PMID 29955607, 2018). "With regard to the CAF model, patient-derived normal and according cancer-associated fibroblasts revealed a conserved gene expression, defined by increased transcript levels of ACTA2, COL1A1, TNC, VEGFA and ALDH1A3, with concomitant decreased expression of CAV1, CD44 and VIM in CAFs." (PMID 28372546, 2017). "Vimentin was present in the spindle-shaped cells in the peritumor stroma, which are commonly recognized as stromal fibroblasts or further may represent cancer cells that have undergone complete EMT." (PMID 28894989, 2017). "It is well known that epithelial-mesenchymal transition (EMT) is necessary for theprogression of several kinds of cancers, including down-regulating the expression of epithelial marker such as N-cadherin, and up-regulating the expression of mesenchymal markers such as E-cadherin and vimentin." (PMID 28035066, 2017). "Epithelial-mesenchymal transition (EMT), a process by which cancer cells lose their epithelial properties and acquire mesenchymal phenotypes such as motility and invasiveness, is activated synergistically by a number of factors including Slug, Snail, E-cadherin, Twist, and vimentin." (PMID 27863406, 2017). "Furthermore, using cell line models, it has been shown that highly concentrated fibrinogen can induce epithelial-mesenchymal transition (EMT) by increasing the expression of vimentin and reducing expression of E-cadherin, which enhances cancer cell invasion and metastasis." (PMID 28154828, 2017). "Therefore, vimentin is regarded as a critical marker of cancer-related EMT28." (PMID 28831201, 2017). "Nestin expression in cancer cells was immunohistochemically studied in 90 patients with completely resected stage II and stage IIIA NSCLC treated with AC and its association with clinicopathologic parameters, including ABCG2, E-cadherin, and vimentin expression, was evaluated." (PMID 28358810, 2017). "However, the exact role of vimentin in cancer progression remains to be fully elucidated." (PMID 26910370, 2016). "The cause may be that although EMT-TFs factors (e.g.vimentin) have been demonstrated to be vital in the carcinogenesis of various cancers, the aberrant expression of vimentin and its mechanisms may be different in different cancers because of the heterogeneity of cancers." (PMID 27657690, 2016). "Furthermore, it was showed that highly Ki-67 may induce EMT by increasing the expression of vimentin, which enhances cancer cell invasion and metastatic." (PMID 27410033, 2016). "However, additional studies are necessary to delineate the precise mechanisms by which vimentin may contribute to cancer derived exosome-recipient cell interactions." (PMID 27363026, 2016).
cancer (continued). "The epithelial-to-mesenchymal transition (EMT) enhances the mobility of cancer cells, facilitating their distant metastasis, showing suppression of epithelial markers, such as E-cadherin, as well as the overexpression of mesenchymal markers, such as N-cadherin and Vimentin." (PMID 27791203, 2016). "Cancer progression is linked with the process of epithelial-to-mesenchymal transition (EMT), during which epithelial cells lose their cell polarity and cell-cell adhesion and gain migratory and invasive properties by down-regulating E-cadherin and upregulating Vimentin expression." (PMID 26943577, 2016). "Moreover, resistin increased expression of vimentin, a key molecule for cancer cell invasion." (PMID 26729407, 2016). "To determine whether the collagen-dense microenvironment and high COX-2 levels regulate different fibroblast populations known to secrete such factors, we performed quantitative IF with vimentin as a general fibroblast marker and α-SMA as a marker of cancer-associated fibroblasts (CAF)." (PMID 27000374, 2016). "The upregulation of gene products associated with migration and invasion (osteopontin, MMP1, vimentin, filamin-A, and β-actin) and gene products for extracellular matrix molecules and their modulators (fibronectin, collagen, ITGBL1, and MXRA5) reflects the invasive nature of this cancer." (PMID 25861239, 2015). "The spread of disease in many cancers has been linked to the expression of EMT transcription factors, which lead to an invasive phenotype characterized by low expression of epithelial marker E-cadherin (CDH1) and high expression of mesenchymal markers Vimentin (VIM) and N-cadherin (CDH2)." (PMID 25605241, 2015). "Therefore, we investigated the role of vimentin during EMT-related cancer progression." (PMID 25965826, 2015). "One study demonstrated that the expression levels of vimentin were significantly up-regulated in renal cell cancer tissues compared to adjacent non-cancerous tissues, which could enhance migration and invasion activities of cancer cells." (PMID 26184160, 2015). "Cancer cells undergoing EMT downregulate the proteins associated with cell adhesion, such as E-cadherin, and upregulate proteins expressed on mesenchymal cells, such as vimentin, N-cadherin and fibronectin, and transcription factors including Snail, Twist, and Slug as well." (PMID 26284927, 2015). "This co-expression of keratins and vimentin and expression of transcription factor Snail in nuclei of remarkable proportion of keratinocytes under the influence of CAFs indicate that keratinocytes are in epithelial–mesenchymal transition, process so important for cancer cell metastases formation." (PMID 26473842, 2015). "E-cadherin, which inhibits cancer cell migration and invasion, was reduced in B[a]P-treated groups relative to the control group, but expression of metastasis-promoting proteins, including N-cadherin, vimentin, snail, and slug, were induced after B[a]P exposure." (PMID 25325763, 2015). "Carcinoma-associated fibroblasts (CAFs) are critical components of carcinoma-associated stromal cells, which are characterized by the overexpression of α-smooth muscle actin (α-SMA), fibroblast activation protein (FAP), fibroblast surface protein (FSP), and vimentin." (PMID 25909286, 2015). "Analysis of human cancer datasets confirms that elevated WNT gene expression is associated with high levels of CUX1 and GLIS1 and correlates with genes of the epithelial-to-mesenchymal transition (EMT) signature: VIM, SNAI1 and TWIST1 are elevated whereas CDH1 and OCLN are decreased." (PMID 25217618, 2014). "Some proteins, such as Vimentin (VIM), Rho GDP-dissociation inhibitor 1 (Rho GDI), Lysosome-associated membrane glycoprotein 1 (LAMP1) and Membrane-associated progesterone receptor component 2 (PGRMC 2), have been previously identified as potential biomarkers for various cancers." (PMID 25477298, 2014).
cancer (continued). "Vimentin is mainly expressed in cells of mesenchymal origin and has been described as a marker of epithelial-to-mesenchymal transition, which is a phenomenon related to increased invasiveness and resistance of some cancer cells, thus manifesting the progression of cancer." (PMID 23383739, 2013). "Moreover, in these clinical samples, the pretreatment cancers exhibited adenocarcinoma histology with preserved membranous staining for E-cadherin, while positive expression for vimentin was more frequently recognized in advanced, posttreatment cancers, indicating that some tumors underwent the EMT." (PMID 23520479, 2013). "In addition, vimentin is also considered as a novel potential anti-cancer therapeutic target." (PMID 22759679, 2012). "Consequently the cancer stoma is characterized by decreased expression of smooth muscle cell markers such as desmin and smooth muscle actin, and increased fibroblast markers such as vimentin." (PMID 24213323, 2012). "Cancer-related genes such as JAK3 and VIM were upregulated with the increased level of trait-associated genes in spots." (PMID 41123022, 2026). "As CD26 expression can influence EMT induction in cancer, we analyzed the correlation of CD26 with the EMT phase markers E-cadherin, Vimentin, β-catenin, Elastin, Periostin, and Versican." (PMID 41426321, 2025). "Vimentin, as a mesenchymal marker in TNBC, is highly expressed in this BC subtype compared with other subtypes and correlates with cancer invasiveness." (PMID 39858010, 2025). "Vimentin affects the miR‐615‐3p‐PICK1 axis via APA, highlighting its role in cancer progression in TNBC." (PMID 39781570, 2025). "Notably, VIM and TERT, which have shown diagnostic potential in BC studies, did not exhibit statistically significant differences in expression between the CRC and healthy control groups, indicating a divergence in the behavior of these markers between different cancer types." (PMID 40003943, 2025). "The expression levels of ACBD3 are positively correlated with epithelial marker E-Cadherin (CDH1) and negatively correlated with mesenchymal marker Vimentin (VIM) or Zinc Finger E-Box Binding Homeobox 1 (ZEB1) in TCGA LUAD cohort and cancer cell lines." (PMID 40189704, 2025). "Vimentin is a key player in several pathophysiological processes such as cell migration, proliferation, adhesion, stress response, EMT, and cancer metastasis." (PMID 40690373, 2025). "Here we focus on vimentin, a 54 kDa type III IF protein that is broadly expressed by cells of mesenchymal origin, as well as by certain types of cancer cells undergoing epithelial-mesenchymal transition." (PMID 40251523, 2025). "Gold nanoparticles have shown potential in reversing the mesenchymal phenotype in various cancer types by inhibiting EMT markers, such as vimentin and N‐cadherin, while enhancing E‐cadherin expression." (PMID 40895189, 2025). "Expressions of fibronectin and PD-L1 were screened in TEVs and the mRNA levels of vimentin and SMAD3 were also assessed in cancer cells after TEV co-culturing." (PMID 40725070, 2025). "Despite this, they retained strong expression of core stromal markers such as DCN, VIM, LUM, and IGFBP7, which were consistently observed across both ex vivo and in situ fibroblasts compared to the epithelial cancer cells." (PMID 41198614, 2025). "Research on malignant tumors has shown that VIM functions crucially in cell cycle regulation, migration, adhesion, and the epithelial-mesenchymal transition (EMT) process in cancer." (PMID 40256740, 2025). "CNa 29 significantly reduced filamin A cleavage, vimentin expression, TWIST1 transcription, and the expressions of genes related to cancer stemness and increased the efficacy of doxorubicin, a chemotherapy drug commonly used for TNBC in clinical settings." (PMID 40151834, 2025).
cancer (continued). "Collectively, these data identify the hypoxia‐PRMT1‐vimentin axis as a critical driver of experimental metastatic progression and position MS023 as a promising therapeutic candidate for targeting cancer metastasis." (PMID 40884268, 2025). "•LncPTEN1 facilitates Trim16-mediated Vimentin degradation, thereby suppressing EMT and cancer metastasis." (PMID 40521243, 2025). "Cell surface proteins such as E-cadherin, N-cadherin, Syndecan-1 and cytoplasmic proteins such as Vimentin and α-SMA are involved in both embryo implantation and cancer." (PMID 39909974, 2025). "CASC15, an oncogenic factor in tumorigenesis of various cancers including BrC, is known to promote EMT by increasing N-cadherin and vimentin protein levels while decreasing that of E-cadherin via TWIST1." (PMID 40943642, 2025). "NTN1 inhibition also reduced VIM expression and increased E-cadherin expression in GFP-labeled mT4 cancer cells." (PMID 40777309, 2025). "The top three features from the primary tumors were the B cell / NK cell ratio in the cancer core, the density of CD68 macrophages, and the proportion of CD4+ T cells positive for Vimentin." (PMID 39975273, 2025). "CD44 has been shown to physically bind to the vimentin N-terminal head domain in HUVEC cells, and both proteins are overexpressed in cancer cells." (PMID 40806710, 2025). "Vimentin and N-cadherin are crucial markers of EMT transition in cancer cells, and here we found a significant reduction in mRNA levels of Vimentin and N-Cadherin in both FDLT-treated NSCLC cell lines." (PMID 41373888, 2025). "Altogether, our studies provide insight into how cysteine 328 in vimentin dictates mechano-transduction signals to remodel actin cytoskeleton and protect against EMT and cancer growth via modulating lncRNA XIST." (PMID 40690373, 2025). "While E-cadherin downregulation and vimentin upregulation are hallmarks of classical EMT, we observed opposite trends upon knockout of cancer cell EphB4 in vitro and in vivo." (PMID 39489818, 2025). "Our combined immunometric assay and Western blot analyses confirmed the presence of PIVKA-II in sera from patients with both cancer types and uncovered differential co-expression patterns with canonical EMT markers: Vimentin and E-cadherin." (PMID 40806708, 2025). "Cancer cells undergoing EMT exhibit diminished expression of epithelial markers such as E-cadherin and elevated expression of mesenchymal markers like vimentin and N-cadherin." (PMID 40352786, 2025). "Specificity analysis of the target antigen, an altered form of vimentin called, ecto-domain vimentin (EDV), shows it to be limited to cell surface expression on cancer cells." (PMID 40051499, 2025). "Silencing miR-514a-5p can reduce E-cadherin expression, promote Vimentin and N-cadherin expression, and induce the EMT process in cancer cells." (PMID 40109856, 2025). "Immunohistochemically, the hepatic lesion exhibited diffuse vimentin positivity, partial Cam5.2, and scattered INSM-1 expression, suggesting a mesenchymal transition of the carcinoma with partial neuroendocrine differentiation." (PMID 40989881, 2025). "The nuclear translocation of β‐catenin in carcinoma cells can upregulate EMT‐related genes such as N‐cadherin and vimentin." (PMID 40400263, 2025). "Vimentin is a type III intermediate filament protein that occurs not only in eukaryotic mesenchymal cells but also in cancer cells." (PMID 38611032, 2024). "They demonstrated that vimentin depletion in CAFs suppresses the invasion of CAF and the CAF-led invasion of cancer cells in a 3D spheroid assay." (PMID 38730588, 2024). "The identification of novel intermediate filament-binding proteins, and how these change during EMT and upon the addition of ALD-R491, increases our understanding of how vimentin dynamics can regulate EMT, cell invasion, and cancer metastasis." (PMID 39796712, 2024). "Subsequently, we detected the expression of cancer-related fibroblast-specific markers α-SMA, vimentin and FAP in NFs and CAFs." (PMID 38896161, 2024).